VIP (vasoactive intestinal peptide)
Diseases named in the same sentence as VIP in open-access papers (continued):
Sharing a sentence is not in itself a finding about the gene and the disease.
helminth infection (2 papers, 2019 to 2020). "ILC2s are also activated by the neuropeptides vasoactive intestinal peptide (VIP) and calcitonin gene-related peptide (CGRP), although as yet it is unclear if these neuronal effectors play a significant role in ILC2 activation during helminth infection." (PMID 31024526, 2019).
hepatocellular carcinoma (2 papers, 2022 to 2023). A malignant tumor that arises from hepatocytes. "In the current study, we investigated the role of the VIP/VIPR1 signaling in controlling hepatocellular carcinoma (HCC) progression." (PMID 35864952, 2022).
HIV-1 infection (2 papers, 2013 to 2018). The type species of lentivirus and the etiologic agent of acquired immunodeficiency syndrome (AIDS). "Macrophages exposed to VIP or PACAP before HIV-1 infection showed resistance to viral replication, comparable to that observed when the cells were treated after infection." (PMID 29951068, 2018). "Because β-chemokines are potent inhibitors of HIV-1 infection, we evaluated whether VIP and PACAP could also induce macrophage secretion of these molecules." (PMID 23818986, 2013). "Because activation of the receptors VPAC1 and VPAC2 has previously resulted in opposite effects during HIV-1 infection, we initially investigated whether the neuropeptides VIP and PACAP, the natural ligands of those receptors, would also affect HIV-1 replication." (PMID 23818986, 2013). "In conclusion, our findings strengthen the antiretroviral potential of VIP and PACAP and point to new therapeutic approaches to control the progression of HIV-1 infection." (PMID 29951068, 2018). "Our study focused, for the first time, on the ability of the natural peptides VIP and PACAP to modulate HIV-1 infection in a primary target cell, in addition to defining the relative contribution of each of their receptors to this phenomenon." (PMID 23818986, 2013). "Our results suggest that VIP and PACAP and the receptors VPAC2 and PAC1 could be used as targets for developing alternative therapeutic strategies for HIV-1 infection." (PMID 23818986, 2013). "Therefore, we believe that VIP/PACAP-mediated inhibition of HIV-1 infection relies not only on the reduction of virus production but also on the concomitant loss of virus fitness." (PMID 29951068, 2018).
hypothyroidism (2 papers, 2018 to 2020). Abnormally low levels of thyroid hormone. "Hypothyroidism can also induce elevation in vasoactive intestinal peptide, which is capable of increasing PRL secretion." (PMID 29403355, 2018). "On the contrary, no significant variations of VIP levels were observed in GD patients with normal thyroid status (euthyroid patients) or iatrogenic hypothyroidism." (PMID 32747757, 2020).
ischemia (2 papers, 2007 to 2024). A hypoperfusion of the BLOOD through an organ or tissue caused by a PATHOLOGIC CONSTRICTION or obstruction of its BLOOD VESSELS, or an absence of BLOOD CIRCULATION. "VIP can increase the activity of retinal neurons and has potent neurotrophic and protective properties, particularly in cases of retinal injury induced by ischemia, oxidation, and inflammation." (PMID 38279089, 2024).
ischemic stroke (2 papers, 2013 to 2021). A stroke disorder caused by obstruction of blood flow to the brain, due to thrombotic (local blood clot formation) or embolic (due to a blood clot or other material traveling from another site) event. "In particular, it has been described that, after CNS injury as ischemic stroke, mast cells present in the gut release histamine and tryptase activating submucosal neurons and peptidergic neurons to secrete vasoactive intestinal peptide (VIP) which alters the movements of the gastrointestinal tract." (PMID 34357086, 2021). "Moreover, the analysis of PLS VIP and synergistic effects suggested that in the acute stage of ischemic stroke, except for improvement of vascular and nerves environment, the removal of the toxic metabolites is essential for treatment." (PMID 24236065, 2013).
megacolon (2 papers, 2014 to 2023). "The myenteric VIP-neurons may contribute to the development of the megacolon, whereas the submucosal VIP-neurons may enable the patients to survive by maintaining the epithelial barrier." (PMID 25059649, 2014).
Nasal congestion (2 papers, 2013 to 2025). Reduced ability to pass air through the nasal cavity often leading to mouth breathing. "Plasma extravasation, and vasodilation caused by mediators such as leukotrienes, prostaglandin D2, nitric oxide, and proinflammatory neuropeptides such as SP, CGRP, and vasoactive intestinal peptide (VIP) create nasal congestion." (PMID 23476696, 2013). "Furthermore, inhibiting the parasympathetic output of the SPG can also regulate vascular tone and glandular secretion, reduce the release of vasodilators such as vasoactive intestinal peptide (VIP) and nitric oxide (NO), and alleviate nasal congestion." (PMID 41383224, 2025).
opsoclonus-myoclonus syndrome (2 papers, 2024 to 2025). Opsoclonus myoclonus syndrome (OMS) is a rare neuroinflammatory disease of paraneoplastic, parainfectious or idiopathic origin, characterized by opsoclonus, myoclonus, ataxia, and behavioral and sleep disorders. "The main paraneoplastic syndromes associated with neuroblastic tumors are opsoclonus-myoclonus syndrome, which occurs in 3% of cases, and diarrhea caused by vasoactive intestinal peptide (VIP) secretion, which occurs in approximately 1% of patients." (PMID 39328672, 2024).
pancreatic (2 papers, 2014 to 2021). "A 63-year-old Caucasian male with a grade 2 (Ki-67 17%) metastatic small bowel neuroendocrine tumor, and a 43-year-old female with a grade 2 (Ki-67 5%) metastatic pancreatic vasoactive intestinal peptide tumor." (PMID 34706762, 2021).
pancreatic ductal adenocarcinoma (2 papers, 1997 to 2022). An infiltrating adenocarcinoma that arises from the epithelial cells of the pancreas. "Immunofluorescence (IF) staining of human PDAC tumors showed increased expression of VIP in pancreatic ductal carcinoma cells with co-expression of cytokeratin-19 (CK19) when compared to adjacent normal tissues." (PMID 36302761, 2022).
pertussis (2 papers, 2025). A contagious bacterial respiratory infection caused by Bordetella pertussis. "Due to the passive transfer of maternal antibodies, ViP is effective in protecting infants aged <2 months from pertussis." (PMID 40365078, 2025). "If it were possible to frame ViP (and the passive immunity conferred) as the infant's “first” pertussis vaccine, this may help to increase uptake and protect the most vulnerable of age groups." (PMID 39906191, 2025).
pneumonia (2 papers, 2024 to 2025). An acute, acute and chronic, or chronic inflammation focally or diffusely affecting the lung parenchyma, caused by an infection in one or both of the lungs (by bacteria, viruses, fungi, or mycoplasma.). "The present study revealed for the first time that plasma levels of neurogenic inflammation-related CGRP and VIP neuropeptides increased and NPY levels decreased in pediatric patients with pneumonia." (PMID 38183438, 2024). "Amygdalin is the key bioactive component of bitter apricot kernel, which exhibits protective effects in an IAV-induced pneumonia mouse model by activating the cAMP/PKA/p-PKA signaling cascade and recapitulating the biological effects of vasoactive intestinal peptide (VIP)." (PMID 41034926, 2025).
primary pulmonary hypertension (2 papers, 2013 to 2014). "Vasoactive Intestinal Peptide (VIP), a pulmonary vasodilator and inhibitor of vascular smooth muscle proliferation, is absent in pulmonary arteries of patients with idiopathic pulmonary arterial hypertension (PAH)." (PMID 23700405, 2013).
prostate tumour (2 papers, 2021 to 2022). "For example, VIP is reported to function via cAMP/PKA in non-tumour cells, and via cAMP/ERK/PI3K in prostate tumour cells." (PMID 35011543, 2022).
renal cell carcinoma (2 papers, 2021 to 2025). "Decrease in MMP2 expression mediated by VIP was also reported in renal-cell carcinoma." (PMID 34208590, 2021). "Though high-affinity receptors for VIP are also present on CAKI-1 renal cell carcinoma (RCC), it was clearly demonstrated that these receptors do not recognize hGHRH and its analogs and display markedly lower or almost negligible binding to GHRH antagonists such as JV-1-42." (PMID 39934495, 2025).
retina degeneration (2 papers, 2010 to 2020). "Besides, VIP neuroprotective effects have been previously observed in retina degeneration both in vitro and in vivo." (PMID 32676122, 2020). "To examine whether early retinal degeneration altered neuropeptide expression in the SCN, we examined the number of VIP-positive cells in CBA/J (n = 7) and CBA/N (n = 5) mice." (PMID 20604961, 2010).
retinal ischemia (2 papers, 2014). A ischemic disease that involves the retina. "In a recent study we have shown that the peptide most closely related to PACAP, namely, vasoactive intestinal peptide (VIP), is also protective in retinal ischemia." (PMID 24900914, 2014).
Rett syndrome (2 papers, 2020 to 2024). A severe neurodevelopmental disorder affecting the central nervous system. "In particular, VIP mutants exhibited a decrease in cortical gamma-range activity, which is associated with cognition and sensory processing and which may be impaired in Rett Syndrome." (PMID 32343226, 2020). "However, nothing is known about the contribution of VIP interneurons to neurodevelopmental dysregulation in Rett Syndrome." (PMID 32343226, 2020). "However, little is known about the role of VIP interneurons in Rett Syndrome." (PMID 32343226, 2020).
Sjögren's syndrome (2 papers, 2009 to 2014). "For the treatment of Sjögren’s syndrome, Interleukin-10 (IL-10), interleukin-17 (IL-17), and vasoactive intestinal peptide (VIP) genes were also transferred to mice." (PMID 26331060, 2014). "In line with this, VIP was proposed as one of the promising approaches for the treatment of Sjögren's syndrome based on VIP gene-transfer experiments in NOD females." (PMID 19356238, 2009).
Stroke (2 papers, 2021 to 2025). Sudden impairment of blood flow to a part of the brain due to occlusion or rupture of an artery to the brain. "Here, the authors show that functional impairments after stroke are associated with the disruption of a highly active subpopulation of interneurons expressing vasoactive intestinal peptide (VIP), which could be ameliorated by chemogenetic stimulation." (PMID 34671051, 2021). "Based on our previous research, SSS maintained BBB integrity by enhancing VIP and its receptors in the brain post-stroke." (PMID 40102879, 2025). "Based on this finding and previous data showing that the return of normal activity patterns in peri-infarct cortex supports behavioral recovery, we used chemogenetics to stimulate VIP neurons once a day from day 4 up to 6 weeks after stroke." (PMID 34671051, 2021). "Second we find that the stroke disrupts sensory responses primarily within a subset of VIP neurons that were highly active/responsive before stroke." (PMID 34671051, 2021). "Collectively, these experiments and analysis indicate that chemogenetic therapy can prevent the stroke-related disruption of sensory responses in VIP neurons." (PMID 34671051, 2021). "GCaMP6s expression was stable over many weeks which allowed us to repeatedly image forepaw-evoked calcium responses in the same VIP neurons before and after targeted stroke to FLS1 cortex." (PMID 34671051, 2021). "Of note, we found that the disruptive effects of stroke and benefits of chemogenetic therapy were mostly experienced within a subset of highly active VIP interneurons." (PMID 34671051, 2021). "Here we chemogenetically augmented VIP interneuron excitability in a murine model of photothrombotic stroke and show that it enhances somatosensory responses and improves recovery of paw function." (PMID 34671051, 2021). "In conclusion, our study enriches current thinking on how stroke and a chemogenetic therapy can influence the function of disinhibitory VIP interneurons." (PMID 34671051, 2021). "On average, approximately 46.8 ± 11.0% of all VIP neurons and 45.3 ± 8.7% of all trials imaged before stroke were classified as responsive to forepaw stimulation." (PMID 34671051, 2021). "Following the induction of stroke, there was a notable reduction in the responsiveness of VIP neurons in the peri-infarct cortex of control treated mice." (PMID 34671051, 2021). "Mice were then randomly selected to receive sham or photothrombotic stroke targeted to FLS1 cortex adjacent to where VIP neurons were imaged." (PMID 34671051, 2021). "First we show that stimulation of VIP neurons with an excitatory DREADD can enhance weakened sensory responses in the stroke affected cortex and improve recovery of sensori-motor paw function." (PMID 34671051, 2021). "Our study, while comprehensive in its breadth of approaches for studying the influence of stroke on VIP interneuron function and how they can affect recovery, has its limitations." (PMID 34671051, 2021). "Interneurons expressing vasoactive intestinal peptide (VIP) represent an intriguing stroke target because they can regulate cortical excitability through disinhibition." (PMID 34671051, 2021). "Here we used longitudinal calcium imaging to examine how stroke affects sensory responses within VIP interneurons." (PMID 34671051, 2021). "Using longitudinal calcium imaging, we discovered that stroke primarily disrupts the fidelity (fraction of responsive trials) and predictability of sensory responses within a subset of highly active VIP neurons." (PMID 34671051, 2021). "In the present work, we hypothesized that chronic stimulation of VIP interneurons could help restore cortical excitability after stroke and promote the recovery of forepaw sensorimotor function." (PMID 34671051, 2021). "In the context of stroke, chronic upregulation of VIP interneuron excitability with chemogenetics may increase the gain of weak sensory or motor forelimb signals, similar to that described in visual cortex." (PMID 34671051, 2021).
Stroke (continued). "Since chemogenetic stimulation of VIP neurons could enhance cortical responses to forepaw stimulation after stroke, we next assessed whether this approach could facilitate the recovery of sensori-motor paw function." (PMID 34671051, 2021). "Based on the rationale that VIP interneurons could act as a disinhibitory circuit and thus potentially restore cortical responsiveness after stroke, we first characterized the effects of excitatory hM3Dq stimulation on VIP neurons in mouse somatosensory cortex." (PMID 34671051, 2021). "Furthermore, this variability raises the interesting question of whether chemogenetic stimulation works by recruiting less responsive or inactive VIP neurons after stroke, or perhaps re-instates the function of those that were generally active and involved in forelimb sensory processing." (PMID 34671051, 2021). "Indeed, the enhanced recovery of forepaw abilities in stimulated mice was not evident until the 2nd week after stroke whereas VIP circuits were functionally back “on-line” at 1 week." (PMID 34671051, 2021). "The idea that activating a subset of interneurons (such as those that express VIP or subpopulations therein), could play an influential role in stroke-related cortical plasticity and recovery, is not without precedence." (PMID 34671051, 2021). "We did not run an additional CNO treated control group (e.g. CNO injections in mice that do not express hM3Dq) given our previous experiments showing that CNO injection, in the absence of hM3Dq, has no detectable effect on VIP neuron excitability or recovery from stroke." (PMID 34671051, 2021).
ulcer (2 papers, 2014 to 2018). "Immunoreactivity was also studied in the smooth muscle underlying the ulcer, where an upregulation of PACAP and VIP could be observed from day 10, along with an upregulation of PACAP and VIP mRNA in the myenteric ganglia in the ulcer’s neighborhood." (PMID 29615974, 2018). "In a model of experimental ulcer, induced by local injection of acetic acid, PACAP and VIP immunohistochemistry was performed during the healing process." (PMID 29615974, 2018).
uveitis (2 papers, 2011 to 2015). An inflammatory process affecting a part of or the entire uvea. "By contrast, patients who had experienced uveitis displayed significantly higher levels of VIP." (PMID 25711477, 2015). "Thus, intravenous delivery of VIP by liposomes would be helpful in the treatment of uveitis and other immune-mediated eye diseases by modulating the immune microenvironment of the ocular region." (PMID 21490757, 2011). "When this patient was excluded, serum VIP levels in patients with uveitis did not exceed the median concentration in the whole population." (PMID 25711477, 2015). "Nevertheless, among patients with uveitis, the patient with the highest VIP levels did not fulfill the criteria for SpA." (PMID 25711477, 2015).
22q11.2 deletion syndrome (1 paper, 2025). 22q11.2 deletion syndrome (DS) is a chromosomal anomaly which causes a congenital malformation disorder whose common features include cardiac defects, palatal anomalies, facial dysmorphism, developmental delay and immune deficiency. "Mice modelling the 22q11.2 deletion syndrome—known to have SWM learning deficits—recapitulate this altered VIP interneuron activity and show reduced vHPC input targeting of VIP interneurons." (PMID 40777258, 2025).
acute appendicitis (1 paper, 2022). "In the appendix, Di Sebastiano examined appendectomy specimens of 15 cases of non-acute appendicitis for the alterations in peptidergic innervation for VIP and GAP-43 using immunohistochemical methods." (PMID 35741196, 2022). "The non-acute appendices were characterized by an increased expression of GAP-43 and larger amounts of SP-immunoreactive and VIP-immunoreactive nerves in the mucosal layer, as compared to appendices with acute appendicitis." (PMID 35741196, 2022).
acute renal failure (1 paper, 2022). "Paraneoplastic hypercalcemia, moreover, rarely causes dehydration up to the development of acute renal failure (2.4%); dehydration is often caused by diarrhea triggered by vasoactive hormones such as VIP." (PMID 36294693, 2022).
adrenal tumor (1 paper, 2014). "Immunohistochemistry analysis of the adrenal tumor was strongly positive for CgA, synaptophysin and VIP." (PMID 25081061, 2014).
age-related hearing loss (1 paper, 2021). "Therefore, it could be of interest to test whether VIP and PACAP have similar potencies to protect auditory neurons against noise- ototoxic drug-induced and age-related hearing loss." (PMID 33828461, 2021).
AIDS (1 paper, 2015). A syndrome resulting from the acquired deficiency of cellular immunity caused by the human immunodeficiency virus (HIV). "The small homology (five amino acids) between VIP peptide sequences and the variable region V2 of HIV-1 gp120 suggest that VIP and their receptors might potentially participate in the pathogenesis of AIDS." (PMID 26779028, 2015).
Alcoholism (1 paper, 2021). "At last, we conducted logistic regression analysis and concluded that alcoholism, GAS, VIP, MTL, CCK, miR-155, and miR-21 were the risk factors of patients with AP." (PMID 34950438, 2021). "Alcoholism, GAS, VIP, MTL, CCK, miR-155, and miR-21 were the risk factors of patients." (PMID 34950438, 2021). "The differential indicators in single factors (alcoholism, GAS, VIP, MTL, CCK, miR-155, and miR-21) were included and assigned." (PMID 34950438, 2021).